MTOR (mechanistic target of rapamycin kinase)
Diseases named in the same sentence as MTOR in open-access papers (continued):
Sharing a sentence is not in itself a finding about the gene and the disease.
pulmonary hypertension (29 papers, 2007 to 2025). Increased pressure within the pulmonary circulation due to lung or heart disorder. "This review highlights that the development of pulmonary hypertension (PH) is linked to the activation of the mTOR pathway, which contributes to vascular remodeling by promoting the proliferation of pulmonary artery smooth muscle and endothelial cells." (PMID 39456805, 2024). "Recently, reports showed that Tacrolimus, an inhibitor of mTOR, was associated with increased Smad1/5/8 signaling in cultured Alk1 knock-down endothelial cells and in an Alk1−/+ mouse model of HHT and pulmonary arterial hypertension." (PMID 39899215, 2025). "As such, further studies are merited on the potential of mTOR-therapeutic targets for the treatment of pulmonary hypertension." (PMID 39684570, 2024). "Pharmacological experiments in animal models support that mTOR inhibition can prevent the development of pulmonary hypertension." (PMID 39456805, 2024). "Another study in OSA patients also revealed the possible role of mTOR in the development of pulmonary hypertension through alteration of the gut microbiota, which is associated with sleep disruption." (PMID 39456805, 2024). "Under this condition of chronic hypobaric hypoxia, overactivation of mTOR has been described in studies in murine models, simulating 5000 m of altitude, which is attributed to the development of pulmonary hypertension." (PMID 39456805, 2024). "In our research, the PI3K/AKT/mTOR pathway was activated in pulmonary artery hypertension, and we believe that Rac1 plays an important role in this process." (PMID 35962329, 2022). "Studies have confirmed that highly expressed mTOR inhibits the proliferation of PAECs by blocking autophagy and alleviates the progression of hypoxia-induced pulmonary hypertension." (PMID 35962329, 2022). "In conclusion, our data demonstrated that inhibition of ROCK and mTOR pathways with H-1337 suppressed the progression of pulmonary vascular remodeling, pulmonary hypertension, and right ventricular remodeling." (PMID 35011628, 2021). "The results of animal experiments with Su/Hx rats suggested that H-1337 administration suppressed the phosphorylation of MLC and mTOR in the SMCs of pulmonary arteries and attenuated pulmonary hypertension and pulmonary vascular remodeling." (PMID 35011628, 2021). "The potential importance of the mTOR signaling pathway for regulating proliferation and survival of VSMCs and in development of vascular remodeling in pulmonary hypertension has been suggested." (PMID 30518907, 2019). "We identified a differential role of mammalian target of rapamycin (mTOR) complex 1 and complex 2, two functionally distinct mTOR complexes, in the development of pulmonary hypertension (PH)." (PMID 30623134, 2018). "Mammalian targeting of rapamycin (mTOR) signaling has been shown to play a role in protein translation and participate in the progression of pulmonary hypertension." (PMID 26120832, 2015). "There is emerging evidence for the mTOR signalling network playing an important role in a number of processes critical for development of pulmonary vascular remodelling in pulmonary hypertension and pulmonary arterial hypertension." (PMID 24069341, 2013). "Another study further indicated that mTOR activation could drive cell senescence, generate the senescence-associated secretory phenotype (SASP), and induce emphysema and pulmonary hypertension." (PMID 41142782, 2025). "While previous studies have shown that mTOR inhibitors can cause interstitial pneumonitis, we also included COPD and pulmonary hypertension due to the theoretical risk that other pulmonary toxicity may be present." (PMID 38435956, 2024). "In addition, perivascular fat produced by obesity is the main cause of vascular resistance to adiponectin, leading to AMPK inhibition and the contribution of pulmonary hypertension via mTOR." (PMID 39456805, 2024).
pulmonary hypertension (continued). "The role of mTOR hyperactivation on the LAM mesenchymal cell/EC axis is particularly significant, as mTOR pathway activation has been recently implicated in the progression of pulmonary vascular remodeling in pulmonary hypertension (PH)." (PMID 38127441, 2023). "The role of mTOR in pulmonary hypertension it is not fully understood." (PMID 33692478, 2021). "We had, therefore, successfully aimed to inhibit this pathway through usage of rapamycin which potently inhibits mTOR to not only prevent but also reverse vascular remodeling processes and right ventricular signs of pulmonary hypertension in mice held under hypoxic conditions." (PMID 17319968, 2007). "Mice with an over-expression of mTOR rapidly develop emphysema, pulmonary hypertension, and pulmonary inflammation, while low-dose rapamycin could inhibit mTOR expression, thereby inhibiting cellular senescence and inflammatory senescence-associated secretory phenotypes." (PMID 36506578, 2022). "In conclusion, H-1337 and H-1337M1 exert inhibitory effects on the ROCK and mTOR pathways in hPASMC and the pulmonary vasculature in Su/Hx rats and may contribute to attenuation of pulmonary hypertension and remodeling of the pulmonary vasculature and RV in Su/Hx rats." (PMID 35011628, 2021). "Taken together, our study indicates that AMPKα2 isoform plays an important role in regulation of PASMCs proliferation by modulating mTOR/Skp2/p27Kip1 axis, and suggests that activation of AMPKα2 might have potential value in the prevention and treatment of pulmonary arterial hypertension." (PMID 27258250, 2016). "In pulmonary hypertension models, SESN3 mediates FOXO1-induced autophagy and suppresses mTOR activity." (PMID 40507985, 2025). "For instance, pulmonary vascular remodeling in pulmonary arterial hypertension (PAH) is tied to dysregulated Wnt/β-catenin, HIPPO, PI3K/Akt/mTOR, and activin signaling pathways." (PMID 39821606, 2025). "Previous work showed an obvious downregulation of of mTOR in lung tissues from patients with pulmonary arterial hypertension (PAH) which was reverted in specific adenovector, mTOR overexpressing mice." (PMID 33692478, 2021). "Therefore, the link between miR-100 and mTOR has significant implications for PASMC proliferation, remodeling and pulmonary hypertension." (PMID 39456805, 2024). "In conclusion, circDiaph3 plays an important role in promoting the proliferation of pulmonary artery smooth muscle cells in rats with pulmonary hypertension through IGF1R and PI3K/AKT/mTOR signaling pathways, suggesting the potential value of circDiaph3 in the treatment of pulmonary hypertension." (PMID 37705862, 2023). "In addition, coincident studies indicate that the inhibition of mTOR by AMPK exerts a protective effect by decreasing the development of pulmonary hypertension; thus, under this CIHH condition, the activation of mTOR inhibitory pathways is also a promising cardiovascular therapeutic target." (PMID 39456805, 2024). "Furthermore, the importance of miR-92b-3p modulation to mTOR signaling-mediated cellular responses will provide invaluable insight for therapeutic approaches to abnormal VSMC proliferation, triggering vascular remodeling in hypoxia-induced pulmonary hypertension." (PMID 30518907, 2019).
tuberculosis (29 papers, 2012 to 2025). A chronic, recurrent infection caused by the bacterium Mycobacterium tuberculosis. "The present study systematically screened PTB patients for SNPs in autophagy-related genes of the PI3K/AKT/mTOR pathway and then used a case-control study to evaluate their associations with tuberculosis susceptibility." (PMID 37493735, 2023). "We know the interplay between M. tb and mTOR during infection is complex, and by understanding this pathway and how they associate with each other in the system, we can learn new targets of study and further develop novel therapies to treat tuberculosis." (PMID 39457551, 2024). "The identification of drugs that inhibit mTOR activation opens new avenues for host-directed therapies, marking a significant step forward in combating tuberculosis and other mycobacterial diseases." (PMID 38912807, 2024). "The results showed that all significant annotated proteins were mapped to 18 KEGG pathways, notably lysosome, tuberculosis, phagosome, apoptosis, the mTOR signalling pathway, and autophagy." (PMID 38029268, 2023). "The phosphoinositide 3-kinase/protein kinase B/mammalian target of rapamycin (P13K/AKT/mTOR) pathway plays a key role in tuberculosis (TB) pathogenesis and infection." (PMID 37998388, 2023). "mTOR is an early host resistance factor in tuberculosis that prevents mitochondrial damage and protects macrophages by increasing mitochondrial energy metabolism fueled by glycolysis." (PMID 36103894, 2022). "Pharmacological inhibition of the AKT/mTOR pathway in host reduces intracellular growth of M. tuberculosis in human PBMCs and in vivo in a model of murine tuberculosis." (PMID 33627504, 2021). "According to the KEGG database, we gained 211 pathways, among which some enriched terms were involved in T2DM, such as “fc gamma R-mediated phagocytosis”, “tuberculosis”, “synaptic vesicle cycle”, “lysosome”, and “mTOR signaling pathway”." (PMID 32596376, 2020). "While mTORC1 was also recently identified as a driver of foam cell biogenesis in tuberculosis, the relevance of mTOR signaling in schistosomiasis remains to be elucidated." (PMID 31681260, 2019). "Moreover, rapamycin, a prototypical mTOR inhibitor, was found to boost long-lived T-cell memory and cytokine recall responses when used as an adjuvant to tuberculosis subunit vaccines in mice." (PMID 41012109, 2025). "Moreover, calcium signaling pathway, herpes simplex virus one infection, mTOR signaling pathway, pathway in cancer, and tuberculosis were significantly enriched by the marker genes." (PMID 35620059, 2022). "This clinical trial is, to our knowledge, the first of an mTOR inhibitor in tuberculosis." (PMID 33740465, 2021). "Functional analysis showed that differentially expressed lncRNA (DElncRNA) and differentially expressed circRNA (DEcircRNA) may play important roles in the mTOR signaling pathway, lysosomal pathway, apoptosis pathway, and tuberculosis pathway." (PMID 32596376, 2020). "Moreover, the peripheral blood mononuclear cells (PBMCs) and CD4+CD25+FoxP3+Treg cells isolated from active tuberculosis patients demonstrated mTOR inhibition during infection." (PMID 29441052, 2018). "Indeed, the PI3K/Akt/mTOR signaling pathway was impaired in the T lymphocytes of patients with active tuberculosis." (PMID 30356420, 2018). "Furthermore, enhanced expression of PPAR-γ has been reported in adipogenesis, and this was shown to be mTOR-dependent, which raises the question as to whether PPAR-γ plays a role in mTORC1-mediated foam cell formation in tuberculosis." (PMID 31681260, 2019). "Therefore, utilizing an mTOR inhibitor could counteract the effect of M. tuberculosis infection on mTOR and provide a novel HDT for TB." (PMID 33903099, 2021).
ulcerative colitis (29 papers, 2014 to 2026). An inflammatory bowel disease involving the mucosal surface of the large intestine and rectum. "Dysregulation of mTOR phosphorylation and autophagy-related proteins has been identified in inflamed colonic tissues from patients with active ulcerative colitis and is associated with TLR4-MyD88 signaling." (PMID 39770669, 2024). "The combination of glucocorticoids and mTOR signaling deficiency or the mTOR signaling inhibitor rapamycin significantly alleviated the formation of acute ulcerative colitis and chronic colitis-associated cancer in later stages." (PMID 32290362, 2020). "Proanthocyanidin A1 has been shown to alleviate DSS-induced ulcerative colitis by regulating autophagy through the AMPK/mTOR/p70S6K signaling pathway." (PMID 40144517, 2025). "In a related study on a DSS-induced ulcerative colitis (UC) model, inhibition of the mTOR axis significantly reduced the expression of TNF-α, IL-1β, and iNOS, leading to improved conditions." (PMID 40077417, 2025). "Cell and mouse experiments have shown that E. bicyclis extract can prevent experimental ulcerative colitis by inhibiting the PI3K/Akt/mTOR pathway, inhibiting inflammation, and regulating the intestinal microbial composition." (PMID 40077417, 2025). "The role of auto-predation in regulating inflammation is also crucial, with recent studies linking the TLR-MyD88 and mTOR pathways to intestinal mucosal destruction and attenuation of ulcerative colitis development." (PMID 39770669, 2024). "Inflammatory conditions, i.e., ulcerative colitis (UC) and Crohn’s disease (CD), demonstrate that mTOR activity in IECs is activated by microbial-derived pathogen-associated molecular patterns (PAMPs), thereby exacerbating inflammation." (PMID 39769296, 2024). "Unexpectedly, Dex injection induced epithelial cell mTOR signal activation and exacerbated experimental ulcerative colitis induced by DSS." (PMID 36032134, 2022). "We found that BMSCs can induce Treg differentiation by inhibiting the Akt/mTOR pathway via PD-L1; this significantly improved symptoms and pathology in our ulcerative colitis rat models." (PMID 36261682, 2022). "Due to the decreased activity of AMPK in the current model of ulcerative colitis, the mTOR activity was enhanced, which also led to an activation in NLRP3 inflammasome expression." (PMID 34489707, 2021). "Consistently, our study showed that although Dex treatment did not alter the expression of GR in intestinal cells, Dex treatment upregulated mTOR activation, mostly in intestinal epithelial cells, in acute experimental ulcerative colitis." (PMID 32290362, 2020). "Taken together, these results strongly suggest that glucocorticoids are helpful for mTOR signaling expression in intestinal epithelial cells and are involved in the regulation of mTOR signaling in the early stages of acute ulcerative colitis." (PMID 32290362, 2020). "In addition, the occurrence of ulcerative colitis (UC) and juvenile intestinal polyposis syndrome (JPS) is also associated with abnormal expression of MTOR." (PMID 40559953, 2025). "Inhibition of p-mTOR expression can treat ulcerative colitis and reduce intestinal damage." (PMID 38977864, 2024). "In the current ulcerative colitis model, the increased expression of mTOR and IL-6 in the colon of ulcerative rats enhanced the generation of Th17 cells and the release of IL-17 and IL-23 in line with reducing the expression of IL-10, the anti-inflammatory cytokine." (PMID 34489707, 2021). "Furthermore, our study also showed that mTOR signaling in intestinal epithelial cells is critical for maintaining immune homeostasis in acute DSS-induced ulcerative colitis." (PMID 32290362, 2020). "Thus, these pieces of evidence indicate that glucocorticoid-induced mTOR signaling in epithelial cells is required in the early stages of acute ulcerative colitis by modulating the dynamics of innate immune cell recruitment and activation." (PMID 32290362, 2020).
ulcerative colitis (continued). "Patients with pre-neoplastic conditions, such as ulcerative colitis, who are undergoing a solid organ transplant might benefit from the use of mTOR inhibitors given their intrinsic anti-tumor properties." (PMID 29915171, 2018). "Moreover, PACs exert their therapeutic effects on ulcerative colitis in mice via the phosphatidylinositol 3-kinase (PI3K)/AKT/mammalian target of rapamycin (mTOR) pathway, which is a key signaling mechanism involved in the regulation of inflammation and immune responses." (PMID 40144517, 2025). "Thus, intestinal epithelial cell mTOR is critical for Dex-induced severe ulcerative colitis." (PMID 32290362, 2020).
acute leukemia (28 papers, 2012 to 2025). A clonal (malignant) hematopoietic disorder with an acute onset, affecting the bone marrow and the peripheral blood. "In a meta-analysis of the genetic polymorphisms of mTOR and cancer risk, the mTOR rs2295080 G allele was associated with a significantly higher risk of acute leukemia in the recessive model and a lower risk of genitourinary cancers in the dominant model." (PMID 36980552, 2023). "In a meta-analysis of the genetic polymorphisms of mTOR and cancer risk, mTOR rs2295080 G allele was associated with a significantly higher risk of acute leukemia in the recessive model and a lower risk of genitourinary cancers in the dominant model." (PMID 37446128, 2023). "In line with that, in 2016 a meta-analysis was performed covering 20 mTOR SNPs and it was found that several of the SNPs were associated with increased cancer risk like acute leukemia." (PMID 35788771, 2022). "Reduced GSK-3β expression has been previously associated with the development of acute leukemia in mice where removal of GSK-3β expression lead to aggressive AML through altered Wnt/Akt/mTOR signalling." (PMID 28918518, 2017). "This shortfall may be due to the lack of targetable mutations, as all major components of PI3K/AKT/mTOR have a lower frequency of mutations or copy number variations (CNV) in acute leukemia than in other cancer types." (PMID 26056603, 2015). "The feasibility of our approach to measuring mTOR inhibition provides a platform for testing other agents that primarily or secondarily inhibit mTOR activity in acute leukemia." (PMID 37958304, 2023). "Currently, emerging molecular targeted therapy is being used in clinic, such as inhibitors of FMS-like tyrosine kinase 3 (FLT3) and mammalian target of rapamycin (mTOR) in acute leukemia." (PMID 29456860, 2018). "To understand how cells display resistance to the dual PI3K/mTOR inhibitor, we used a panel of 25 acute leukemia cell lines." (PMID 29951132, 2018). "Taken together, our data suggest that acute leukemia cells resistant to PI3K/mTOR inhibition display upregulation of a GPCR, P2RY14, which has a role in patient survival and also couples to the activation of ERK signaling." (PMID 29951132, 2018). "This review attempts to summarize key findings leading to aberrant activation and to reflect on both promises and challenges of targeting PI3K/AKT/mTOR in acute leukemia." (PMID 26056603, 2015). "Preclinical evidence points to a significant role of PI3K/AKT/mTOR signaling for initiation and maintenance of acute leukemia." (PMID 26056603, 2015). "Considerable efforts have led to numerous clinical trials of PI3K/AKT/mTOR inhibition in cancer, including in acute leukemia." (PMID 26056603, 2015). "The inhibition of PI3K/AKT/mTOR signaling suppressed the ribosomal protein S6 (RPS6) in acute leukemia subjects." (PMID 26275051, 2015). "Treatment with the mTORC1 inhibitor rapamycin achieved a reduction of leukemic burden as well as prolonging survival in diseased mice implying PI3K/AKT/mTOR signaling in leukemogenesis of PTEN− acute leukemia." (PMID 26056603, 2015). "Aberrant activation of PI3K/AKT/mTOR pathway has been identified as a feature of LICs in acute leukemia." (PMID 26056603, 2015). "Our emphasis lies on the insights gained through high-throughput data acquisition that open up new avenues for identifying specific subgroups of acute leukemia as ideal candidates for PI3K/AKT/mTOR targeted therapy." (PMID 26056603, 2015). "Nevertheless, mutations in membrane-associated genes upstream of PI3K/AKT/mTOR are frequent in acute leukemia and are associated with aberrant activation of PI3K/AKT/mTOR thus providing a good rationale for further exploration." (PMID 26056603, 2015). "Given the overall convincing preclinical data on PI3K/AKT/mTOR signaling in acute leukemia, the results of clinical trials have been rather disappointing." (PMID 26056603, 2015).